GPR33 (G protein-coupled receptor 33)
Description:
Orphan receptor; could be a chemoattractant receptor.
Tractability: Small molecule: it belongs to a druggable protein family. Antibody: UniProt places it where antibodies can reach, with medium confidence; UniProt predicts a signal peptide or a membrane-spanning region; its Gene Ontology location is reachable by antibodies, with medium confidence.
Gene: Protein-coding gene on chromosome 14 (31,482,875 to 31,488,039, reverse strand). Ensembl gene ENSG00000214943.
Subcellular location: Cell membrane
Gene Ontology:
Molecular function: complement receptor activity; G protein-coupled receptor activity
Biological process: complement receptor mediated signaling pathway; inflammatory response; phospholipase C-activating G protein-coupled receptor signaling pathway; positive regulation of cytosolic calcium ion concentration; G protein-coupled receptor signaling pathway; signal transduction
Cellular component: plasma membrane; membrane
Genetic constraint (gnomAD): Loss-of-function variants: 11 observed, 12.17 expected, observed/expected ratio (o/e) 0.9, 90% interval 0.57 to 1.49. The upper end of that interval is the gene's LOEUF score, 1.49, which puts it in group 6 of 6, group 1 being the genes least tolerant of losing a copy. Missense variants: 357 observed, 373.76 expected, observed/expected ratio (o/e) 0.96, 90% interval 0.88 to 1.04. Synonymous variants: 131 observed, 136.28 expected, observed/expected ratio (o/e) 0.96, 90% interval 0.83 to 1.11.
Homologues: Orthologues: chimpanzee GPR33 (99% identical), macaque GPR33 (95% identical), dog GPR33 (77% identical), pig GPR33 (76% identical), rabbit GPR33 (76% identical), mouse Gpr33 (72% identical), guinea pig GPR33 (71% identical). Paralogues in human: CMKLR1 (34% identical), C3AR1 (32% identical), FPR2 (30% identical), FPR3 (30% identical), FPR1 (29% identical), GPR32 (28% identical), C5AR1 (27% identical), C5AR2 (20% identical).
Diseases named in the same sentence as GPR33 in open-access papers:
GPR33 is named in the same sentence as 3 diseases in open-access papers, as found by Europe PMC text mining. Sharing a sentence is not in itself a finding about the gene and the disease. The quoted sentences say what the papers report.
epidermolysis bullosa simplex (1 paper, 2021). Epidermolysis bullosa simplex (EBS) is a group of hereditary epidermolysis bullosa (HEB) disorders characterized by skin fragility resulting in intraepidermal blisters and erosions that occur either spontaneously or after physical trauma. "Diseases associated with its human orthologous GPR33 (G protein-coupled receptor 33) include epidermolysis bullosa simplex with nail dystrophy and multiple epiphyseal dysplasia." (PMID 34281170, 2021).
GPR33 also shares sentences with these, for which no sentence is quoted: multiple epiphyseal dysplasia (1 paper); Nail dystrophy (1).